RAD51 (RAD51 recombinase)
Diseases named in the same sentence as RAD51 in open-access papers (continued):
Sharing a sentence is not in itself a finding about the gene and the disease.
tumor (continued). "In fact, low levels of RAD51 have been shown in PTEN knockout mice and PTEN-/- human tumor cells." (PMID 37509303, 2023). "Therefore, many clinical trials have investigated HR repair as a potential target for tumor therapy, including ATR, ATM, and Rad51." (PMID 37684630, 2023). "Several strategies have been developed to distinguish BRCA-like from non-BRCA-like tumours, including detection of BRCA1 mutation, genomic scar assays or functional testing of HR capacity by measurement of RAD51 foci." (PMID 37029129, 2023). "Interestingly, RAD51 and ARHGEF28 have previously been identified as a tumour suppressor and an oncogene respectively." (PMID 35931958, 2022). "In the case of HR typical for DNA repair in both irradiated and nonirradiated tumor cells, the expression level of the primary gene involved, RAD51, and the level of its protein product were studied in irradiated and nonirradiated tumor cells." (PMID 35992802, 2022). "In addition to directly targeting Rad51 protein, destruction of the protein-protein interaction between BRCA2 and Rad51 can also impair HRR and mediate cell death for development of anti-tumor strategies." (PMID 35875146, 2022). "RAD51 plays a central role in the DDR process, and thus represents a promising anti-tumor target." (PMID 35646698, 2022). "Defects in homologous recombination pathway-related genes RAD54, RAD51 and RAD52 could lead to tumour development." (PMID 35689754, 2022). "The authors propose that this is due to the role of RAD51 in inducing fork reversal, but no research has described a role of RAD51 in fork progression under unperturbed conditions in these tumor cells." (PMID 35969531, 2022). "Furthermore, defects in DNA repair and damage response genes such as RAD51, KU80 SIRT1, NFAT5, and REV3L, or ESCC tumor cells expressed higher CLDN4 to harbor stem-like properties are also the potential CCRT resistance mechanisms." (PMID 35457185, 2022). "Tumor cells, with basal replication stress under unperturbed conditions, are more dependent on RAD51 activity than non-transformed cells for accurate DNA replication." (PMID 35969531, 2022). "High expression of DSB repair-related genes (MRE11A, Rad50, RAD51, and XRCC2) in HNSCC patients may contribute to tumor acquisition and progression or induce drug-resistant phenotypes." (PMID 36338767, 2022). "RAD51 inhibitor also inhibited tumor growth in subcutaneous mouse model of EAC without any toxicity to mice as well as significantly potentiated cytotoxicity of DNA breaking agent in vivo." (PMID 36428789, 2022). "Multiple Rad51 mediators and interactors participate in HRR of tumor cells." (PMID 35875146, 2022). "In the present study, we found that the mechanism of VPA in normal cells was opposite to tumor cells, RFWD3-dependent Rad51 ubiquitination was down-regulated, which means that VPA-mediated radioprotection was associated with preserving Rad51 activity and avoiding its ubiquitination by RFWD3." (PMID 33842359, 2021). "The absence of RAD51 foci before or after one course of chemotherapy did not correlate with significantly more tumor reduction compared to tumors with RAD51 foci present." (PMID 33670893, 2021). "The advantage of this approach is that the absence of RAD51 foci in geminin-positive tumor cells actually reflects an inability to perform HR and is not due to the absence of proliferation in the biopsy." (PMID 33670893, 2021). "PCI-24781 significantly inhibited tumor growth and downregulated DNA repair machinery (BRCA1, CHK1, RAD51, and O6-methylguanine-DNA- methyltransferase (MGMT)), increasing DNA double-strand breaks and causing apoptosis in the GBM cell lines, including an MGMT expressing cell line in vitro." (PMID 34696786, 2021). "A variety of BRCA1-proficient tumour types also display high levels of nuclear RAD51 without DNA damage induction, which suggests a role for RAD51 overexpression in tumorigenesis and possibly chemotherapy resistance." (PMID 34316709, 2021).
tumor (continued). "Time-dependent increased RAD51, FEN1 and UNG expression levels were confirmed after LPS stimulation, which may contribute to tumor cell fitness." (PMID 33446690, 2021). "In order to better comprehend how Rad51 proteins are expressed in HCC, the HPA database was utilized to analyze Rad51 expression in HCC, and the outcomes explained that tumor tissues expressed higher protein levels of Rad51 in comparison to normal samples in HPA039310 with antibodies." (PMID 34115569, 2021). "Since HRR is a dynamic process and relates to cell cycle, false positive HRD results can arise when tumor cells are senescent, as, owing to cell cycle arrest, they have absent RAD51 nuclear foci irrespective of BRCA status." (PMID 34702316, 2021). "The absence of chemotherapy induced RAD51 foci in geminin positive tumor cells was taken as a sign of HRD." (PMID 34702316, 2021). "We now propose to establish whether the use of FFPE material can serve as a reliable substitute for fresh tumor tissue, comparing fresh tumor specimens and matching archival FFPE tumor blocks on RAD51 scores, ideally in large cohorts of different tumor types." (PMID 33003546, 2020). "Combined treatment of ATO with irradiation also reduced colonies formation in UW402 tumor cells, which was independent of DNA damage repair proteins Rad51 and Ku86." (PMID 32321992, 2020). "Combined, these patient tumor data indicate that primary GBM tumors do not incur PTEN-dependent expression changes neither in RAD51 nor its paralogs and retain functional DNA damage signaling, including HR and NHEJ activity." (PMID 33138032, 2020). "In some hypoxic tumor cells, the expression of homologous recombination repair (HRR) pathway-related genes, such as RAD51 and BCRA1, will be downregulated, while the expression of non-homologous end-joining (NHEJ) pathway-related genes, such as ATM and DNA-PKcs, will be upregulated." (PMID 32974200, 2020). "While the RAD51 protein has a recovery effect, it can also enhance the antidamage and invasion abilities of tumor cells because of its nonselective properties." (PMID 32190537, 2020). "However, when the RAD51 gene was knocked-down in the CSC, its sensitivity to PARP inhibitors and radiation therapy increased, which effectively inhibited tumor growth." (PMID 32190537, 2020). "Abnormal expression of RAD51 and RAD52 can contribute to genomic instability and tumor progression." (PMID 31719794, 2019). "Given that Rad51 and BRCA1 play a central role in HR-mediated DSB repair and govern the response of tumor cells to cisplatin, we wondered whether let-7e regulates BRCA1 and Rad51 expression in EOC." (PMID 28376831, 2017). "Nonclinical studies have shown RAD51 to be a potential predictor of tumor resistance in SCLC treatment." (PMID 29113403, 2017). "For example, the Brca2G25R/G25R MEFs exhibited a mild defect in RAD51 recruitment and fork protection but the survival of mice was not affected except they had a mild increase in tumor formation at 24 months of age." (PMID 27490902, 2016).
tumor (continued). "Surprisingly, there is no statistical difference between RAD51 expression in T tissues and the clinical characteristics, including age, gender, tumor grade, tumor stage, tumor TNM stage and lymphatic metastasis." (PMID 27566579, 2016). "Assessing the number of nuclear foci of RAD51, FANCD2 and γH2AX may help to establish DDR cellular competence, before, during and after treatment with IR and PARP inhibitors, to predict tumor sensitivity or acquired resistance to treatments." (PMID 27884198, 2016). "Here we demonstrate that RAD54 translocase depletion and/or RAD51 overexpression in human tumor cells results in the accumulation of RAD51 foci that do not co-localize with markers of DNA damage." (PMID 25765654, 2015). "Intriguingly, RAD51 is commonly expressed at relatively high levels in human tumor cells compared to noncancerous cells and the nuclei of these cells contain elevated levels of spontaneous RAD51 foci compared with nontumor cells." (PMID 25765654, 2015). "Next, we evaluated whether metformin affected DNA repair pathways in vivo by immunohistochemically examining the expression of Rad51 and ERCC1 in tumor samples." (PMID 26599019, 2015). "Additionally, we confirmed the expression of Rad51 and ERCC1 by immunoblotting tumor samples from the in vivo study." (PMID 26599019, 2015). "Expression of RAD51, a crucial player in homologous recombination (HR) and DNA double-strand break (DSB) repair, is dysregulated in human tumors, and can contribute to genomic instability and tumor progression." (PMID 26230935, 2015). "RAD51 levels are elevated in a wide variety of human tumor cell lines when compared to nontransformed primary cell lines." (PMID 25765654, 2015). "In the seven cases exhibiting heterogeneous staining patterns, there was no expression of Rad51 in the shallow level, while positive expression was observed in the middle and deep levels of the tumor." (PMID 24065387, 2014). "Tumor cells lacking functional BRCA1 and BRCA2 are deficient in the repair of DSBs by RAD51-mediated HR, which leads to cell cycle arrest and/or cell death." (PMID 24625059, 2014). "Our results indicate that over-expression of the XRCC3 gene is also associated with an invasive behaviour in vitro and the promotion of tumour formation in vivo, these features were independent of RAD51 and the proliferation rate of the cells." (PMID 21283680, 2011). "Rad51 and γH2AX stains were not performed on tumor specimens before EC in two patients because of insufficient tumor sample after reserving stocks for clinical use." (PMID 20205718, 2010). "As well, RAD51 foci may not always align with PARPi sensitivity because the drug response can also be shaped by compensatory repair pathways, tumor heterogeneity, and the cell cycle context." (PMID 41520277, 2026). "All three PE samples revealed γH2AX‐positivity in tumor cells, but only in samples from patients PL‐TUE #01 (no HRD) and PL‐TUE #02 (no HRD) we also detect RAD51‐positivity in tumor cells showing signs of DNA damage (RAD51+/γH2AX+) while residing in S/G2‐phase (RAD51+/γH2AX+ x CyclinA+)." (PMID 40456663, 2025). "Analysis via the TISCH2 database indicated predominant expression of RAD51 in Tprolif and malignant cell clusters, suggesting its involvement in promoting OSCC progression through regulation of malignant phenotypes and remodelling of the tumour microenvironment (TME)." (PMID 41350246, 2025).
tumor (continued). "The tumor tissue slides showed all therapeutic groups contained sufficient amount of MNFs inside the tumor, and the remarkable therapeutic outcome can be attributed to the synergistic effects of GLUT-1 inhibition and the increase in IRF-1, which leads to downregulation of RAD51 expression." (PMID 38693181, 2024). "Like in the olaparib arm, individual grafts that responded to CBP were predominantly BRCA1-foci-negative/RAD51-foci-negative and, interestingly, most grafts of the BRCA-foci-negative/RAD51-foci-positive model b3977, whose response to olaparib was mediocre, showed tumor size reduction under CBP." (PMID 37007122, 2023). "We showed here that RAD51 inhibitors could also be considered and that, for instance, therapies combining B02 and compounds that inhibit DNA repair, such as PARP inhibitors, could target increased tumor cell death." (PMID 35969531, 2022). "Thus, the patterns of RAD51 expression were significantly different in tumor-cell cultures pre-exposed (GO1) or not pre-exposed (Sus\fP2) to radiation." (PMID 35992802, 2022). "Although the remarkable efficacy of SFXN4 knockout in inhibiting tumor growth in vivo precluded assessment of the combined effects of drug treatments and SFXN4 inhibition in vivo, immunohistochemical staining of tumors revealed that nuclear RAD51 was lower in SFXN4 knockout tumors than in controls." (PMID 36402786, 2022). "We have previously shown that RAD51 is present at the replication forks of non-transformed human cells under both non-stress conditions and dNTP depletion induced by hydroxyurea (HU), consistent with reports in yeast and tumor cells." (PMID 35969531, 2022). "Notably RAD51 was also induced in response to chemotherapy alone in both cell lines and as it is centrally located in each network it is a rationale target in TNBC tumours that often display chemoresistance heterogeneity." (PMID 34316709, 2021). "We also include an analysis of the genomic and transcriptomic landscape of the DDR PARP genes and key HR genes (BRCA1, BRCA2, ATM, RAD51, MRE11, PALB2) in GI patient tumours (n = 1744) using publicly available datasets to identify patients that may benefit from PARPi therapeutic approaches." (PMID 34440228, 2021). "Moreover, O6BG abolished CDDP-activated RAD51 and p-BRCA1 expression in tumor specimens." (PMID 33397362, 2021). "This study is the first to unequivocally demonstrate that PTEN deficiency is not linked to the RAD51 expression or the HR activity amongst primary neural and non-neural Pten-null cells, PTEN-deficient tumor cell lines, and primary PTEN-mutant GBM patient-derived tissue specimens and BTICs." (PMID 33138032, 2020). "In the setting of fixed tissue without information on whether tumor cells are actually trying to repair DSBs, the lack of RAD51 protein expression will not be sensitive for the diagnosis of HRD." (PMID 32192091, 2020). "Consistent with the result of in vitro experiment, the PDX model tumor burden of three treatment groups illustrated that when combined with miR-509-3, Olaparib was more effective in reducing tumor burden in two PDX cases (PDX1 and PDX9) along with the decline in RAD51 positive rate." (PMID 32005272, 2020). "Importantly, we further show that the RAD51 assay is feasible in routine formalin‐fixed paraffin‐embedded (FFPE) tumor samples without prior induction of DNA damage." (PMID 30377213, 2018). "However, in tumor cells, the increase in Rad51 expression was not as notable in scratched cells as it was in fibroblasts." (PMID 28151479, 2017). "One key molecular determinant of tumour cell response to PARP inhibition is the ability to localise the DNA recombinase RAD51 to the site of DNA damage, a critical event in HR repair that can be monitored by the immunodetection of DNA damage induced RAD51 foci." (PMID 25883215, 2015). "No significant relation was observed between the tumor grade, and expression of Rad51 or BRCA2." (PMID 25909291, 2015).
tumor (continued). "Notably, these results cannot be explained by effect of RAD51 on cell growth, as RAD51 depletion did not effect cell proliferation and doubling time in vitro and primary tumor growth in vivo in MDA-MB231 xenografts." (PMID 24811120, 2014). "However, some studies have found BRCA2-associated tumours to be negative for HER2 and to over-express CHEK2 (checkpoint kinase 2) and RAD51 (homolog of Saccharomyces cerevisiae Rad51)." (PMID 18275599, 2008). "One hypothesis proposes that RAD51 should have essential roles, independent of its mediator/accessory proteins, and whose ablation would be too detrimental for the cells’ survival, impairing their development, and thus, tumor development." (PMID 37190078, 2023). "Based on this evidence, one could propose that because RAD51 possesses both BRCA1/2/PALB2-dependent and BRCA1/2/PALB2-independent functions during replication, its inactivation would be more toxic than that of one of the loading factors, thus impairing the proliferation of tumour cells." (PMID 34316706, 2021). "Interestingly, we also observed strong co-staining of FGFR4 and RAD51 in surgical specimens of patients who have not responded to neoadjuvant radiotherapy indicating that specifically those tumor cells that expressed high FGFR4 and upregulated RAD51 had survived the radiation treatment." (PMID 27650548, 2016). "Given that more extensive RAD51 structures form in S33 cells upon RAD51 overexpression than in the other tumor lines in which RAD51 levels are not artificially elevated, the results suggest that induction of RAD51 overexpression in S33 yields a relatively high level of RAD51 expression." (PMID 25765654, 2015). "In addition to BRCA1 (93.7 ± 6.6% vs 72.8 ± 20.7%, P = 0.0044), significant differences in tumor volume were observed between positive and negative γH2AX (78.4 ± 17.4% vs 65.6 ± 26.8%, P = 0.0429) and Rad51 baseline foci groups (78.1 ± 18.9% vs 63.6 ± 24.4%, P = 0.0351)." (PMID 20205718, 2010). "In addition to a slower replication rate compared to tumour cells, non-cancerous cells like H-6037 display a full complement of DNA repair pathways, thus compensating for the chemically-induced loss of individual DDR pathways and mitigating RAD51-BRCA inhibitor/olaparib impact on cell viability." (PMID 40091075, 2025). "Quantitative PCR analysis confirmed that CCC‐002 markedly downregulated the mRNA expression of RAD51 in KP‐4 cells, while KR12 treatment did not downregulate the RAD51 expression in cultured PDAC cells and KP‐4 tumor tissues." (PMID 36262061, 2023). "The herein presented RAD51-based functional HR (fHR) test on immunostained FFPE sections quantifies real-time function of HR repair in the tumor, does not require high tumor cell content and works on both treatment-naïve and NACT-treated HGSC specimens." (PMID 36805632, 2023). "Although RAD51 foci have been validated as functional markers of HRR and are predictive of PARPi responses, the assay has not been validated across different tumour types as represented by this cohort of PDX models." (PMID 37627223, 2023). "A newly identified PolQ inhibitor Novobiocin resensitized these cancer cells to PARPi in vitro and in vivo by increasing the excessive DSB end resection and nonfunctional RAD51 foci-loading rates in HRD and PARP-inhibitor-resistant tumor cells." (PMID 36253861, 2022). "The clinical development of a dynamic biomarker of HRD, such as RAD51 foci quantification, will greatly increase our understanding of the level of HRD remaining in tumours re-gaining HRR without losing their BRCAm status." (PMID 35008208, 2021). "Consistent with this, we too found that lack of Rad51 upregulation by both SK-MES-1 and HCC1806 SG-sensitive tumor lines correlates with known SG in vivo sensitivity." (PMID 33196706, 2020).